CD40LG (CD40 ligand)
Diseases named in the same sentence as CD40LG in open-access papers (continued):
Sharing a sentence is not in itself a finding about the gene and the disease.
coronary artery disease (47 papers, 2007 to 2025). "The black rice pigment fraction significantly decreased plasma levels of soluble vascular cell adhesion molecule-1 (sVCAM-1), soluble CD40 ligand (sCD40L), and high sensitivity C-reactive protein (hs-CRP) in patients with coronary heart disease." (PMID 34917106, 2021). "Soluble CD40 ligand levels (sCD40L) in patients without and with the primary and secondary endpoints in the subgroup of patients with angiographically-proven coronary artery disease (n = 459)." (PMID 26237513, 2015).
asthma (45 papers, 2012 to 2025). "Gene ontology and Kyoto Encyclopedia of Genes and Genomes analyses showed that the differentially expressed genes, HLA-DMB, IL4, HLA-DPB1, and CD40LG, were related to the occurrence of asthma, and HLA-DMB expression was significantly reduced in allergic asthma." (PMID 34714718, 2021). "The relevance between the FEO‐03 network and asthma on the KEGG Pathways database presented EPX, IL4, IL5, IL13, CD40LG, TNF, and IL10 according to p value." (PMID 40777200, 2025). "The increased expression of CD40 ligand that we observed in the asthma group compared with the control group could also relate to the presence of elevated type 1 cytokines since IL-12 has been demonstrated to be produced as a result of enhanced CD40/CD40L interactions." (PMID 23043798, 2012). "As we known, LPS, as a bacterial product, leads to T-independent (TI) responses, while anti-CD40 mimics CD40 ligand (CD40L, also known as CD154) expressed by antigen-stimulated T cells and reflects the course of asthma characterized by Th2 cell-mediated responses." (PMID 32636842, 2020).
leukemia (44 papers, 1982 to 2025). A malignant (clonal) hematologic disorder, involving hematopoietic stem cells and characterized by the presence of primitive or atypical myeloid or lymphoid cells in the bone marrow and the blood. "Subsequent studies have identified that miR-155 and miR-125b also repress BCL2 through the interactions with its 3′ UTR and partially mediate proliferation and cell cycle arrest response to CD40 ligand (CD154) in human leukemia B-cells." (PMID 29361709, 2018). "Next, we asked whether activation of CD28- and/or CD40LG-mediated signaling reverses BACH2OE-induced low leukemia burden." (PMID 38233409, 2024). "Myeloid leukemia cells can be induced to differentiate into DCleu by using various stimulants, such as GM-CSF plus IL-4 with either TNF-α or CD40 ligand (CD40L)." (PMID 35074008, 2022). "Since BACH2OE xenografts showed low leukemia burden in the BM, we then wondered whether these events are mediated by reduced CD28 and/or CD40LG levels in T-ALL cells upon BACH2 overexpression." (PMID 38233409, 2024).
hyper-IgM syndrome (43 papers, 2009 to 2025). A primary immune deficiency disorder characterized by defective CD40 signaling; via B cells affecting class switch recombination (CSR) and somatic hypermutation. "CD40 ligand deficiency, characteristic of hyper IgM syndrome, disrupts immunoglobulin class switching, impairing B-cell function and increasing vulnerability to severe infections." (PMID 39997452, 2025). "One participant (C124) initially investigated for CVID/other IEI, was diagnosed with Hyper-IgM-Syndrome (HIGM) following the identification of a pathogenic variant in the CD40 ligand gene (described elsewhere)." (PMID 40455168, 2025). "Hyper IgM syndromes are a group of primary immunodeficiency disorders caused by defects in the CD40 ligand or CD40-signaling pathway, leading to impaired B-cell proliferation, immunoglobulin class switch recombination (CSR), and germinal center formation." (PMID 39886113, 2024). "The structural model of CD40LG indicated that all mutations caused the X-linked hyper-IgM syndrome with pulmonary alveolar proteinosis to be located within the tumor necrosis factor homology domain." (PMID 37173671, 2023). "We describe a five-month-old boy with CD40LG mutation (c.516T > A, p.Tyr172Ter) X-linked hyper-IgM syndrome with pulmonary alveolar proteinosis as the first manifestation." (PMID 37173671, 2023). "Hyper-IgM syndrome (HIGM) is caused by various genetic lesions of the CD40/CD154 (also known as the CD40 ligand (CD40L)) axis." (PMID 36986378, 2023). "The most frequent form of hyper-IgM syndrome (accounting for 70% of all cases) is X-linked hyper-IgM, where T cells lack functional CD40 ligand and cannot signal B cells to switch." (PMID 35440951, 2022). "Four children (P4, 10, 16 and 17) were confirmed to have hyperimmunoglobulin M syndrome (HIGM) because they identified mutations or microdeletions in the CD40LG gene." (PMID 33743629, 2021). "The hyper-IgM syndrome is either an inherited X-linked PID due to mutations in the gene encoding CD40 ligand or autosomal recessive PID due to mutations in CD40, AID or UNG genes." (PMID 27642394, 2016). "Hyper immunoglobulin M syndrome is a consequence of mutations in the CD40 ligand (CD40L) gene, also known as tumour necrosis factor superfamily 5 genes (TNFSF5) situated on the X chromosome at q26." (PMID 39886113, 2024). "X‐linked hyper‐IgM syndrome (XHIGM; OMIM: 308230) is the most frequently occurring form of hyper‐IgM syndrome and is associated with mutations in the gene encoding CD40 ligand (CD40L)." (PMID 34114358, 2021). "No cases of hyper-IgM syndrome (HIGM) due to X-linked CD40 ligand (CD40L) deficiency were reported." (PMID 30697212, 2018). "CD40L mutations lead to CD40 ligand deficiency, which can lead to a rare X-linked recessive primary immunodeficiency disorder, hyper-IgM syndrome (HIGM), characterized by normal or elevated serum IgM levels and reduced or absent levels of other immunoglobulins." (PMID 38028622, 2023).
liver disease (43 papers, 2008 to 2025). "Cryptosporidium species was identified in only 2 cases, one of whom had cholangitis and liver disease, which is normally associated with MHC class II or IL-21/IL-21 receptor deficiencies but also described in CD40 ligand and CD40 deficiency." (PMID 27555459, 2017).
depression (41 papers, 2013 to 2026). "Weighted gene co-expression network analysis and machine learning identified CD40LG as a potential molecular bridge between depression-associated immune modules and MASLD." (PMID 41595706, 2026).
respiratory infections (41 papers, 2010 to 2025). "X-linked hyper-immunoglobulin M (XHIGM), a primary immunodeficiency syndrome caused by mutations in the CD40 ligand gene(CD40LG), presents with recurrent respiratory infections in pediatric patients." (PMID 36419145, 2022).
primary immunodeficiency (38 papers, 2008 to 2025). "In the chronic infection stage, specific targeted mRNAs Cd40 and Cd40lg were upregulated and significantly enriched in pathways associated with immunosuppression, including autoimmune thyroid disease and primary immunodeficiency pathways." (PMID 38229193, 2024). "CD40LG deficiency is a severe primary immunodeficiency caused by mutations in the CD40L gene, which can lead to T‐cell impairment, B‐cell defects, and susceptibility to opportunistic pathogens." (PMID 35092700, 2022). "CD40 ligand (CD40L) deficiency or X-linked HIGM syndrome is a severe primary immunodeficiency caused by mutations in the CD40L gene and characterized by susceptibility to life-threatening infections." (PMID 34335625, 2021). "X‐linked hyper‐immunoglobulin M (IgM) syndrome (X‐HIGM or HIGM1, OMIM#308230) is a primary immunodeficiency caused by inactivating mutations of CD40LG gene." (PMID 33475257, 2021). "The X-linked hyperimmunoglobulin M syndrome (HIGM), caused by mutations in the CD40LG gene, is a kind of primary immunodeficiency disease (PID)." (PMID 27818686, 2016). "In particular, mutations in CD40LG, CD40, AICDA, or UNG cause hyper-IgM (HIGM) syndrome, a heterogeneous group of primary immunodeficiencies." (PMID 30131802, 2018).
endothelial dysfunction (36 papers, 2006 to 2025). In vascular diseases, endothelial dysfunction is a systemic pathological state of the endothelium (the inner lining of blood vessels) and can be broadly defined as an imbalance between vasodilating and vasoconstricting substances produced by (or acting on) the endothelium. "Others are associated with anti-inflammation (IL-10 and TRAIL) or endothelial dysfunction (CD40 ligand, EGF)." (PMID 33138839, 2020). "First, PM2.5 is associated with biomarkers including systemic inflammation, thrombosis, and endothelial dysfunction, which are associated with elevated fibrinogen, C-reactive protein, white blood cell count, activation markers P-selectin, and soluble CD40 ligand." (PMID 35837365, 2022). "Activated platelets also release CD40 ligand (CD40L) and other mediators, triggering an inflammatory response in the endothelium, which results in endothelial dysfunction." (PMID 37240434, 2023). "There are several well-known circulating biomarkers related to inflammation and endothelial dysfunction, including high-sensitivity C-reactive protein (hsCRP), soluble form of P-selectin (sP-selectin), soluble CD40 ligand (sCD40L), and monocyte chemoattractant protein-1 (MCP-1)." (PMID 33640001, 2021).
lung carcinoma (35 papers, 2009 to 2025). "As result, we identified five target genes of metformin (RPS6KA5, RORA, SH3BP5, NUPR1, and CD40LG), which were significantly correlated with favorable prognosis and immune infiltration in lung cancer patients." (PMID 39135791, 2024). "The in vivo analysis revealed that the incorporation of CD40 ligand significantly boosted the immunogenicity of Trop2-CD40L VLPs against lung cancer, resulting in more effective tumor control and an increased survival rate in Lewis (Trop2+) tumor-bearing mice." (PMID 38948057, 2024). "CD40 ligand-modified lung cancer cell exosomes effectively activate DCs, inhibit lung cancer progression, and prolong survival in mice." (PMID 37122754, 2023). "CD40LG (CD40L, TNFSF5, CD154), one of the most well-studied TNFSF, has been a therapy target in cancer treatment and is typically associated with the prognosis of lung cancer." (PMID 36437961, 2022). "The CD40 ligand modified exosome of lung cancer cells have activated DCs effectively, inhibited the progress of lung cancer and prolonged the survival time of mice." (PMID 32025211, 2020). "CD40LG not only could promote the apoptosis of lung cancer cells, but also may be involved in regulating T cell function." (PMID 39135791, 2024). "The bioinformatics analysis identified five favorable prognostic MTGs (RPS6KA5, RORA, SH3BP5, NUPR1, and CD40LG) for NSCLC patients, all of which was downregulated in lung cancer tissues as compared with normal tissues." (PMID 39135791, 2024). "Trop-2 cell surface glycoprotein is overexpressed in lung cancer and has recently been used as an effective immunotherapeutic target along with the CD40 ligand (CD40L)." (PMID 34104817, 2021).
tetanus (35 papers, 2011 to 2025). A serious infectious disorder that follows wound contamination by the Gram-positive bacterium Clostridium tetani. "Among them, CD40LG (CD40 ligand) is closely associated with 5 vaccines: diphtheria toxoid vaccine, cholera vaccine, tetanus toxoid vaccine, chickenpox vaccine, and inactivated poliovirus vaccine." (PMID 24209834, 2013).
Sjögren’s syndrome (33 papers, 2009 to 2026). "CD40–CD154 (CD40 ligand) interaction in the co-stimulatory pathway is involved in many (auto)immune processes and both molecules are upregulated in salivary glands of Sjögren’s syndrome (SS) patients." (PMID 23300544, 2012).
acute coronary syndrome (32 papers, 2008 to 2025). Signs and symptoms related to acute ischemia of the myocardium secondary to coronary artery disease. "Soluble CD40 ligand (sCD40L) is a protein that plays a crucial role in the inflammatory response associated with the development and progression of acute coronary syndrome (ACS)." (PMID 39331861, 2024). "In our study, we have identified soluble CD40 ligand (sCD40L) as a potential predictor for acute coronary syndrome (ACS)." (PMID 39331861, 2024). "The concentration of these C-reactive protein, myeloperoxidase, soluble CD40 ligand and placental growth factor were significantly increased in acute coronary syndrome patients." (PMID 26576922, 2015). "This study aimed to investigate the differences in level of several biomarkers, i.e. C-reactive protein, myeloperoxidase, soluble CD40 ligand and placental growth factor, between acute coronary syndrome and chronic stable angina patients." (PMID 26576922, 2015). "Soluble CD40 ligand levels (sCD40L) in patients without and with the primary and secondary endpoints in the subgroup of patients with acute coronary syndrome (n = 125)." (PMID 26237513, 2015).
neutropenia (32 papers, 2008 to 2026). A decrease in the number of neutrophils found in the blood. "Neutropenia is a common complication in boys with CD40 Ligand deficiency." (PMID 20180797, 2010). "Given the potential problems with stem cell transplantation, an alternative approach for boys with CD40 ligand deficiency is to adopt a waiting brief; treating with immunoglobulin and cotrimoxazole and monitoring closely for complications such as liver disease and neutropenia." (PMID 20180797, 2010). "Patient 5 had impaired expression of CD40 ligand on activated CD4+ T cells and also neutropenia, which are common findings in this PID." (PMID 24198970, 2013).
colitis (31 papers, 2010 to 2025). Inflammation of the colon. "In another model of colitis, in TCR-alpha-deficient transgenic mice, B-cell deficiency exacerbates disease and only CD40 ligand-activated B-cells can adoptively transfer protection and suppress the colitis inflammation." (PMID 29774025, 2018).
HIV-1 infection (31 papers, 2009 to 2025). The type species of lentivirus and the etiologic agent of acquired immunodeficiency syndrome (AIDS). "We previously reported on a lentiviral vector–based DC therapeutic vaccine for HIV-1 infection using a vector that coexpressed the CD8+ T cell epitope together with CD40 ligand (CD40L)." (PMID 35972807, 2022). "We provide evidence that the peripheral IFN-alpha production in HIV-1 infection is actively suppressed by the enhanced interaction of CD40 ligand (CD40L), a member of the tumor necrosis factor family, and its receptor CD40, which are both upregulated upon immune activation." (PMID 22470494, 2012).
inflammatory bowel disease (31 papers, 2006 to 2025). A spectrum of small and large bowel inflammatory diseases of unknown etiology. "Rag-/-/SCID: Recombination activating genes knockout model/severe combined immunodeficiency; TNF: Tumor necrosis factor; UC: Ulcerative colitis; TLR: Toll-like receptors; Treg cells: Regulatory T cells; CD40LTG: CD40 ligand transgene; IFNγ: Interferon-gamma; IBD: Inflammatory bowel disease." (PMID 36039239, 2022).
metabolic syndrome (31 papers, 2008 to 2026). A cluster of metabolic risk factors for CARDIOVASCULAR DISEASES and TYPE 2 DIABETES MELLITUS. "Changes in CD40 ligand have also been tested in two studies, with only one 8-week RCT of twice-per-week fasting in 39 adults with metabolic syndrome, demonstrating a meaningful reduction in CD40 ligand vs. control after 8 weeks." (PMID 36296982, 2022). "In a group of 30 healthy volunteers and 30 patients with the metabolic syndrome, adiponectin concentration correlated negatively with plasma soluble P-selectin and soluble CD40 ligand (CD40L) levels, as well as with epinephrine- and ADP-induced platelet aggregation." (PMID 25123549, 2014). "As an example, in healthy adults, the consumption of PS-enriched soy milk reduced lipid peroxidation and inflammatory markers, whereas in individuals with metabolic syndrome the PS treatment did not affect inflammatory biomarkers such as CRP, VCAM, ICAM, IL-6, CD40 ligand, E-selectin, and MCP-1." (PMID 32455866, 2020).
Cirrhosis (30 papers, 2009 to 2025). A chronic disorder of the liver in which liver tissue becomes scarred and is partially replaced by regenerative nodules and fibrotic tissue resulting in loss of liver function. "On Lasso analysis, the parameter most highly correlated with HCC development was history of hepatic decompensation, followed by sICAM-1 MFI, presence of cirrhosis, granulocyte-macrophage colony stimulating factor MFI, and soluble CD40 ligand MFI." (PMID 28894136, 2017).
fungal infections (30 papers, 2012 to 2025). "Recently, Pamela P. Lee discussed endemic mycoses in IEI, in which she highlighted T. marneffei infection in CD40 ligand deficiency in Southeast Asia." (PMID 36159645, 2022). "Consequently, uncontrolled exogenous fungal infections further activate platelets and cause platelet-related CD40 ligand (CD40L) release." (PMID 41364521, 2025).
periodontitis (29 papers, 2012 to 2026). An acute or chronic inflammatory process that affects the tissues that surround and support the teeth. "Cytidine-phosphate-guanosine oligodeoxynucleotide (CpG ODNs) and CD40 ligand (CD40L), which are agonists of Tlr9, suppressed periodontal inflammation and bone loss in the alveolus of WT mice with induced-periodontitis." (PMID 34445604, 2021). "Regarding intestinal tissue analyses, higher levels of IL-1β, IL-4, IL-6, IL-17A, IL17F, IL-21, IL-31, IL-33 and soluble CD40 ligand (sCD40L) were found in patients having IBD activity and periodontitis." (PMID 34501547, 2021).
schizophrenia (29 papers, 2006 to 2025). A major psychotic disorder characterized by abnormalities in the perception or expression of reality. "Nevertheless, a larger study found that general cognitive abilities may be associated with IL-1Ra and sTNF-R1 in schizophrenia and with soluble CD40 ligand (sCD40L) and IL-1Ra in bipolar disorder patients." (PMID 30349492, 2018).
Opportunistic infection (28 papers, 2011 to 2025). An infection that is caused by a pathogen that would generally not be able to cause an infection in a host with a normal immune system. "CD40 ligand-deficient patients suffered from opportunistic infections, especially Pneumocystis jiroveci and Cryptosporidium parvum infections." (PMID 36159645, 2022).
Insulin resistance (26 papers, 2012 to 2025). Increased resistance towards insulin, that is, diminished effectiveness of insulin in reducing blood glucose levels. "Previous studies have shown that CD40LG is also closely associated with insulin resistance." (PMID 37744382, 2023).
ovarian carcinoma (25 papers, 2005 to 2025). A malignant neoplasm originating from the surface ovarian epithelium. "Inducing apoptosis via silencing of SMYD3 has also been observed in ovarian cancer in vivo and has been accredited to the upregulation of CD40LG and downregulation of BIRC3." (PMID 33333978, 2020). "Similar effects have been seen clinically in an ovarian cancer patient treated with the adenovirus ONCOS-102 (expressing GM-CSF) and adenovirus expressing CD40-ligand (CD40-L); increased IL-10 was again seen." (PMID 26633468, 2015).
hepatocellular carcinoma (24 papers, 1975 to 2025). A malignant tumor that arises from hepatocytes. "Recent in vitro experiments have unveiled the potential for dendritic cell-based immunotherapy, activated through the CD40/CD40 ligand (CD40L) immune checkpoint, to provoke robust anti-tumor responses not only in CRC, but also in hepatocellular carcinoma and oral cancer." (PMID 37892436, 2023).
chronic kidney disease (23 papers, 2009 to 2025). Impairment of the renal function secondary to chronic kidney damage persisting for three or more months. "Mörtberg and colleagues have recently shown that circulating concentrations of PMPs expressing CD40 ligand were positively associated with the severity of chronic kidney disease, and the concentration of CD40 ligand + PMPs is inversely correlated with estimated glomerular filtration rate (eGFR)." (PMID 33202988, 2020). "As the counterpart of the CD40 ligand, the Cd40 gene was also found to be demethylated in inflammatory CD40+ monocytes in the setting of chronic kidney disease." (PMID 33202988, 2020).